TBK1 (TANK binding kinase 1)
Diseases named in the same sentence as TBK1 in open-access papers (continued):
Sharing a sentence is not in itself a finding about the gene and the disease.
tumor (continued). "Utilizing the immunostaining level of p-TBK1 as a convenient readout, we observed that LiSmore-DCs (indicated by GFP+CD45.2+) from tumor-draining lymph nodes displayed a notable increase in p-TBK1 staining following blue light stimulation." (PMID 37673917, 2023). "Herein, we observed that TBK1 and mTOR inhibitors strongly prevented the TRIM28-induced upregulation of PD-L1 expression and inhibited tumor growth in vivo." (PMID 37357254, 2023). "IHC staining further showed increased protein levels of TET2, cGAS, STING and TBK1 in TET2-overexpressing tumours, in which the protein levels of STING and TBK1 were clearly decreased by RU.521 treatment." (PMID 37667220, 2023). "The authors interpret this result as confirmation that the CLOCK-POSTN-TBK1 axis is involved in tumor angiogenesis and point to the need for further investigation into the precise molecular interaction between CLOCK, POSTN and TBK1." (PMID 38275375, 2023). "STINGVAX, a cancer vaccine comprising CDNs (activating TBK1/IRF3, NF-κB, and STAT6 signaling pathways) and GM-CSF, has shown promising results in different murine tumor models." (PMID 37380989, 2023). "The induction of STING pathway activates downstream IRF3 and TBK1 to drive the inflammatory cytokines and IFN-I production, thereby disrupting the immune tolerant status in tumor niches." (PMID 36879291, 2023). "Western blot results demonstrated that CISP significantly increased the expression of p-TBK1 and p-IRF3 in tumors, indicating that STING signal pathway in tumor sites was activated." (PMID 37607938, 2023). "On the contrary, we found that treatment with GPC3144‐152 peptide in the co‐culture of CD8+ T cells with TYST or TYST‐sh‐cGAS cells significantly enhanced the levels of TBK1 and IRF3 phosphorylation in these tumor cells, even after silencing cGAS." (PMID 37986544, 2023). "BX-795, functioning as a PDK-1/TBK-1 inhibitor, blocks PDK1/Akt signalling within tumour cells, thereby inhibiting their proliferation and inducing apoptosis." (PMID 38049741, 2023). "CRISPR-Cas9 screening identified druggable targets that sensitized tumor cells to IFN-γ when inactivated, such as MCL1 and TBK1, highlighting potential ICB combination therapies in CRC." (PMID 36669486, 2023). "Overexpression of TBK1 and β-catenin in CCA is a strong indicator of high tumour aggressiveness and correlates with poor clinical outcomes." (PMID 36928362, 2023). "The activation of TANK-binding kinase 1 (TBK1), whose insufficient activity would lead to autoimmune, neurodegenerative, or oncogenic diseases, is one of the main anti-tumor mechanisms of RSV." (PMID 35409389, 2022). "Inactivation/loss of PKCλ/ι was found to induce ULK2 activity, which directly activates the TBK1-STING-IRF3 pathway, leading to IFN production and anti-tumor responses." (PMID 35365653, 2022). "In summary, upregulated ALKBH5 plays an oncogenic role in HNSCC by inhibiting RIG-I-mediated IFNα secretion via the IKKε/TBK1/IRF3 pathway, which ultimately reduces immune-killing cell infiltration and promotes tumor progression." (PMID 35395767, 2022). "We developed TBK1/IKKi dual inhibitors, SR8185, 200A, and 200B that show potent anti-tumor activity in human breast, prostate, and oral cancer cells." (PMID 35335873, 2022). "Exploring new avenues for TBK1 targeted therapy in PDAC have shown that Compound II can reduce viability in human PDAC cell lines and reduced tumor burden in a pre-clinical model of KRAS driven PDAC (p48-Cre; LSL-KrasG12D; Cdkn2alox/lox, KIC)." (PMID 34572737, 2021).
tumor (continued). "The abnormal presence of cytosolic DNA from dying tumor cells leads to cGAS activation and the generation of cyclic GMP-AMP, which, upon binding to STING, activates TANK-binding kinase 1 (TBK1) and IRF3, ultimately triggering type 1 interferon signaling." (PMID 33963293, 2021). "We now report the decreased level of IL-6 in HCC tissues treated by TBK1 antagonist as well as the TBK1 expression in HCC and tumor stroma." (PMID 33679751, 2021). "The results indicates that inhibition of NEAT1 results in the increase in cGAS, STING level, and upregulation of phosphorylation of TBK1 and IRF3 in both of cell lines and tumor samples." (PMID 32296457, 2020). "Importantly, the inhibition of FABP5 amplified and sustained the anti‐tumor immune response induced by RFA, with the activation of the STING/TBK1 pathway playing a critical role." (PMID 40956367, 2025). "This analysis revealed an increase of IKKε and TBK1 protein levels in the tumor samples as compared with the normal tissues." (PMID 40738190, 2025). "Activated TBK1 phosphorylates IRF3, promoting its nuclear translocation and initiating IFN-α/β transcription, which rapidly recruits CD8+ T cells and NK cells to elicit anti-tumor effects." (PMID 41019083, 2025). "Given our observation that DS induces a TBK1-dependent but STING-independent activation of IFN-I, we hypothesized that combining DS with a STING agonist could enhance IFN-I signaling in tumor cells, potentially resulting in a synergistic anti-tumor effect." (PMID 40625660, 2025). "Notably, irradiated tumor cells, including CT26, H22, and GL261 cells, exhibited significantly increased phosphorylation levels of TBK‐1 and IRF‐3." (PMID 40470716, 2025). "Meanwhile, PARPi activate the STING/TBK1/IRF3 pathway, resulting in increased expression of chemokines, such as the potent chemoattractants CXCL10 and CCL5, which target CD8+ T cells and enhance the immune response in the tumor microenvironment." (PMID 41460301, 2025). "Nanocarrier‐mediated FABP5 deletion was found to promote RFA‐induced ferroptosis and anti‐tumor immune responses, including increased infiltration of CD8+ T cells and effector memory T cells, through activation of the STING/TBK1 pathway and stabilization of TBK1 protein." (PMID 40956367, 2025). "Importantly, the deletion of RPS15AP12 diminishes the expression of RPS15A, leading to the upregulation of anti‐tumour immune responses by activating RIG‐I and MDA5 and downstream p‐TBK1 and p‐IRF3 as well as IFN‐β levels." (PMID 40000433, 2025). "STING activation leads to TBK1 phosphorylation of Ser71 on HPV16 E7 and Ser78 on HPV18 E7, marking them for ubiquitination and degradation via HUWE1, reducing E7 levels and impairing tumor growth." (PMID 39949780, 2025). "Also, in the tumor microenvironment (TME), activation of the TBK1 downstream signaling pathway can contribute to inflammation by enhancing the infiltration and cytotoxic function of CD8+ T cells." (PMID 40076567, 2025). "In vivo experiments using nude mice, both amlexanox treatment and TBK1 knockdown significantly inhibited xenograft tumor growth, and also reduced the levels of EMT-related proteins as well as phosphorylated AKT and NF-κB in the tumor tissues." (PMID 41488647, 2025). "Notably, TBKBP1, a crucial adaptor protein for TBK1, mediates the MTORC1-activated growth factor signaling pathway, which is essential for tumor growth." (PMID 39161768, 2024). "Momelotinib, the sole TBK1 inhibitor undergoing clinical trials in oncology, failed to confer desired anti-tumor benefits through the intended therapeutic molecular mechanism." (PMID 39161768, 2024).
tumor (continued). "Given the vital role of IFN‐I in ME49Δompdc‐induced anti‐tumor immunotherapy, and abolishing GRA4 in ME49 enhances host IFN‐I responses by targeting TBK1, we hypothesized that vaccination with ME49Δompdc/gra4 could be more effective in preventing tumor growth." (PMID 39031880, 2024). "Notably, BIBR1532 intensifies the damage inflicted by IR on DNA, thereby enhancing the phosphorylation of STING, TBK1, and IRF3 proteins in both tumour cells and dendritic cells (DCs)." (PMID 38816831, 2024). "Additionally, it is noteworthy that IRF-7, a transcription factor of a crucial interferon-inducing gene in the TBK1-IFN pathway, has demonstrated anti-tumor effects in some studies, while others suggest the possibility of its pro-cancer effects." (PMID 39161768, 2024). "As TBK1 is indispensable for GRA4 to regulate IFN‐I responses, we next sought to verify whether the anti‐tumor effect of ME49Δompdc/gra4 relies on TBK1." (PMID 39031880, 2024). "Nonetheless, the effectiveness of TBK1 inhibitors for tumor suppression is not universally applicable." (PMID 39161768, 2024). "In addition to antigen-presenting cells, the TBK1-IFN pathway activates innate immune signaling pathways in various immune cells, thereby bolstering the efficacy of tumor immunotherapy." (PMID 39161768, 2024). "TBK1, an abundant and ubiquitous serine/threonine-protein kinase of IκB kinase (IKK) family, has been widely reported to regulate innate immune responses against bacteria and viruses and as a target for tumor treatment." (PMID 39030571, 2024). "Notably, the on‐target inhibition of PARP7 by thioparib‐activated STING/TBK1‐dependent phosphorylation of STAT1, triggered a strong induction of type I interferons (IFNs), and resulted in tumor growth retardation in an immunocompetent mouse model." (PMID 36652375, 2023). "LID + US also significantly increased the percentage of CD80 + DC in the tumor, increased the percentage of CD86 + DC in the tumor-draining lymph nodes, and enhanced the phosphorylation of TBK1 and IRF3, which were related to the activation of STING pathway in the tumor tissue." (PMID 37391428, 2023). "The HER2-AKT oncogenic pathway inhibits cGAS-STING pathway-mediated DNA immune recognition by suppressing STING-TBK1 interaction, as well as TBK1 K63-type ubiquitination, thereby inhibiting type I IFN production, cellular senescence, and apoptosis in tumor cells." (PMID 37153627, 2023). "Moreover, Mn2+ is a powerful cGAS activator to enhance STING-mediated type I IFN response in both tumor cells and DCs, involving STING, tank-binding kinase 1 (TBK1), and interferon regulatory factor 3 (IRF-3) phosphorylation 25,26." (PMID 37221157, 2023). "Moreover, IHC staining showed increased protein levels of TET2, cGAS, STING and TBK1 in TET2-overexpressing tumours, in which the protein levels of STING and TBK1 were clearly decreased by RU.521 treatment." (PMID 37667220, 2023). "Together, the results indicate that tumor cell cytosolic detection of DNA by cGAS catalyzes the generation of 2′–5′ cyclic GMP‐AMP (cGAMP), which binds to STING, allowing it to recruit, phosphorylate, activate TBK1 and IRF3, and produce Type I IFNs." (PMID 37986544, 2023). "The contribution of PARP7 to IFN signaling might be dependent on the tumor type, but it is also possible that low levels of PARP7 are sufficient for an effect on TBK1." (PMID 37077937, 2023). "TAMs-related functions are also regulated by several genes, including C-C motif chemokine ligand 2 (CCL2), C-C motif chemokine ligand 18 (CCL18), TANK-binding kinase 1 (TBK1), and IFN regulatory factor 3 (IRF3), whose signaling pathway is activated during tumor angiogenesis." (PMID 36432658, 2022). "The relationship between TBK1 expression levels and the clinicopathological characteristics of the CRC patients was evaluated, which revealed that the upregulation of TBK1 was significantly correlated with tumor size, lymph node metastasis and TNM stage." (PMID 35637944, 2022).
tumor (continued). "TBK1 inhibition impaired CRC cell proliferation, migration, drug resistance and tumor growth." (PMID 35637944, 2022). "cGAS was found slightly upregulated only in LUAD tumour samples compared to normal tissues (2.511e-06) while TBK1 showed no significant expression changes between tumour and normal samples." (PMID 35794238, 2022). "Nevertheless, the tumor immune roles of TBK1 in myeloid cells, T cells and B cells have not been evaluated in any cancer models." (PMID 35395857, 2022). "Alternatively, dormant tumour cells could also aberrantly increase the expression of several genes, such as ROR2, Axl and TANK binding kinase 1 (TBK1), to facilitate osteoblast-induced tumour cell dormancy." (PMID 36307871, 2022). "Our data revealed that TBK1 predicted poor prognosis in patients with HCC and may be a therapeutic target by attenuating tumor immunosuppression." (PMID 33679751, 2021). "More general, the therapeutic induction of an immunogenic form of tumor cell death will not be achieved by a combination of H-1PV with gemcitabine-like drugs which employ cGAS/STING/TBK1-mediated signaling to trigger IFN production." (PMID 34071585, 2021). "Inhibitor-kappaB kinase epsilon (IKKε) and TANK-binding kinase 1 (TBK1) are non-canonical IκB kinases, both described as contributors to tumor growth and metastasis in different cancer types." (PMID 32630674, 2020). "TBK1.DF_DN is a gene set composed of genes down-regulated as a combination of an over-expressed oncogenic form of KRAS and the suppression of TBK1, a kinase that regulates cell proliferation, apoptosis, autophagy, and anti-tumor immunity." (PMID 32850701, 2020). "TBK1 constitutively interacts with OPTN to act as a key modulator to initiate elimination of damaged mitochondria via selective mitophagy (PINK1/Parkin-dependent mitophagy), that is involved in tumor suppression pathways." (PMID 32514015, 2020). "On the other hand, it is also reasonable that the accumulation of YAP/TAZ, usually caused by the dysregulation of Hippo-YAP pathway, might dampen the TBK1, IRF3 activation, and the anti-tumor responses." (PMID 32174922, 2020). "In addition, the Tank-binding kinase 1 (TBK1), which is responsible for the phosphorylation of IRF3, was phosphorylated in both tumor models after DMXAA treatment." (PMID 31511510, 2019). "Tumor cell-derived DNAs can be detected by one of the major DNA sensors, cyclic GMP-AMP synthase (cGAS) (a cytosolic DNA sensor), which activates STING and then the TBK1 (the major kinase for IRF7 and IRF3 activation) pathway, thus inducing IFN-1 expression." (PMID 31049360, 2019). "Further studies are needed to delineate the whether the interaction between TBK1 and AKT is critical to the mesenchymal phenotype of tumor cells in PDAC." (PMID 31681587, 2019). "In addition, TBK1-II cooperated with lapatinib, a EGFR/HER2 inhibitor, to accelerate apoptosis in vitro and suppress tumor growth in a xenograft model of HER2+ BC." (PMID 25594009, 2014). "Consequently, tumor cells experiencing a loss of TNF-induced RIPK1 S25 phosphorylation exhibit increased RIPK1 activation and fail to recruit non-canonical IKK kinases (TBK1 and IKKε) to the TNFR1 complex." (PMID 41315176, 2025). "Importantly, we found that DS-induced IFN-I activation in tumor cells is dependent on TBK1; silencing TBK1, but not MAVS, STING, or MyD88, abolished DS-mediated IFN-I activation." (PMID 40625660, 2025). "While in various non-immune cells such as liver, kidney, and tumor cells, TBK1 may be more involved in tumorigenesis, cell proliferation, and growth." (PMID 40076567, 2025). "Then, STING polymers recruit and activate TANK-binding kinase 1 (TBK1) which phosphorylates STING and interferon regulatory factor 3 (IRF3) and induces the production of IFN-Is and many other proinflammatory cytokines, regulating the natural anti-tumor-immune-responses in vivo." (PMID 40033359, 2025).
tumor (continued). "DNA sensing is a ubiquitous innate immune pathway in both immune and tumor cells, initiated when cyclic GMP-AMP synthase (cGAS) detects cytosolic DNA and produces 2′3′-cyclic GMP-AMP (2′3′-cGAMP), which activates STING to trigger TBK1/IRF3-dependent IFN-β and ISG expression." (PMID 41148213, 2025). "Immunohistochemistry analysis revealed that lamin-deficient tumor had a comparable STING intensity than the control xenograft, indicating that the STING/TBK1 pathway may not be the downstream mechanism." (PMID 40708945, 2025). "We found that the expression levels of p‐STING, p‐TBK1, p‐IRF3, and p‐STAT1 were markedly increased in the Rfwd3 knockdown group compared to the shNC group, indicating that knocking down Rfwd3 in tumor cells results in activation of the STING pathway in adjacent immune cells." (PMID 41117130, 2025). "Furthermore, TBK1’s role in promoting tumor angiogenesis is supported by studies indicating that TBK1 in cancer cells enhances angiogenesis through a non-cell-autonomous mechanism by upregulating vascular endothelial growth factor (VEGF)." (PMID 39001398, 2024). "We did not observe diminished expression of other immune sensors MAVS and MyD88 or downstream components of these immune pathways TBK1 and IRF3; suggesting that targeting of STING-specific immune responses may be an important strategy to facilitate tumor progression in HPV+ HNSCCs." (PMID 38147007, 2024). "The enhanced TBK1 and IRF3 activation should increase the sensitivity of TYST cells to CD8+ T‐cell‐mediated killing in the co‐culture system while cGAS silencing usually attenuated the cGAS‐STING signaling to reduce IFN‐β production and CD8+ T‐cell infiltration, promoting tumor growth." (PMID 37986544, 2023). "TBK1 was upregulated in human tissues, including intrahepatic (n = 182) and extrahepatic (n = 40) CCA tissues, compared with nontumor tissues, and the elevated expression of TBK1 was positively correlated with larger tumour diameter, lymph node metastasis, and advanced TNM stage." (PMID 36928362, 2023). "Vacant Tumor microparticle induces macrophage conversion to M2 type via cGAS/STING/TBK1/STAT6 pathway, promoting M2 type macrophage proliferation and M1 type macrophage apoptosis, and M2 type macrophages, in turn, promote TRC proliferation, leading to tumor growth and metastasis." (PMID 35861052, 2023). "In addition, TBK1 in immune cells (e.g. DCs and CD8+ T cells) might antagonize antitumor immunity, thus promoting tumor development." (PMID 35395857, 2022). "Recently, Li et al89 reviewed that targeting IKBKE with three TBK1/IKBKE dual inhibitors, including WO2009032861, SAR and Domainex, could powerfully inhibit cell viability and tumor development in human breast, prostate, and oral cancers both in vivo and in vitro." (PMID 31733040, 2020). "To identify molecular alterations in primary ductal tumour cells, we first examined the activation status of NF-κB and Ral signalling via fluorescence-activated cell sorting (FACS) staining for phospho-NF-κB/p65 or phospho-TBK1 (TANK-binding kinase-1) as readouts for the respective pathways." (PMID 32641778, 2020). "Likewise, genetic and pharmacological validation of the hit TBK1 found no reproducible requirement for TBK1 in the growth of KRAS-mutant tumor cell lines in vitro." (PMID 27096871, 2016). "However, in some cases, TBK1 does not always function as an active pro-tumor factor." (PMID 39161768, 2024). "Similarly, we employed Tbk1 siRNA to knockdown TBK1 in vivo, and found that ME49Δompdc/gra4 vaccination could not inhibit tumor growth and prolong host survival time when the host Tbk1 was silenced." (PMID 39031880, 2024).